RN7SL124P (RNA, 7SL, cytoplasmic 124, pseudogene)
Gene: Miscellaneous RNA gene on chromosome 2 (151,372,003 to 151,372,287, forward strand). Ensembl gene ENSG00000242113.
Homologues: Orthologues: chimpanzee Metazoa_SRP (98% identical), macaque Metazoa_SRP (93% identical). Paralogues in human: RN7SL1 (80% identical), RN7SL2 (80% identical), RN7SL3 (79% identical), RN7SL479P (79% identical), RN7SL296P (78% identical), RN7SL664P (78% identical), RN7SL732P (78% identical), RN7SL118P (77% identical), RN7SL186P (77% identical), RN7SL791P (77% identical), RN7SL126P (77% identical), RN7SL386P (77% identical), and 703 more.